UCHL1 (ubiquitin C-terminal hydrolase L1)
Diseases named in the same sentence as UCHL1 in open-access papers (continued):
Sharing a sentence is not in itself a finding about the gene and the disease.
Uterine leiomyoma (1 paper, 2023). The presence of a leiomyoma of the uterus. "In this study, human uterine leiomyoma and myometrial tissues were used to detect the protein and mRNA expression levels of UCHL1." (PMID 36830563, 2023). "We found that UCHL1 expression was considerably higher in uterine leiomyomas than in the myometrium." (PMID 36830563, 2023). "The similarity between the cardiac and uterine hypoxia findings may explain why UCHL1 is upregulated in uterine leiomyomas." (PMID 36830563, 2023). "UCHL1 is one of the molecules that could have a role in the development of uterine leiomyomas in humans." (PMID 36830563, 2023). "For the treatment of uterine leiomyoma, targeting UCHL1 activity may be a unique and possible therapeutic strategy." (PMID 36830563, 2023). "The function of UCHL1 in the etiology of uterine leiomyomas is currently poorly understood." (PMID 36830563, 2023).
Zinc deficiency (1 paper, 2022). A deficiency of the essential metal Zinc; an essential cofactor for many enzymes. "Zinc deficiency has been shown to reduce UCHL1 expression in the rat hippocampus." (PMID 35054106, 2022).
tumor (147 papers, 1991 to 2026). "IncreasedProtein product of UCHL1 (deubiquitinating enzymes).Associated with aggressive neoplasms (colorectal, prostate, gastric, and pulmonary).Further studies are needed." (PMID 40149663, 2025). "Then, the loss of CHGA and UCHL1 increases susceptibility to oxidative stress and inhibits tumour aggression during clinical treatment." (PMID 37246623, 2023). "Overexpression of UCHL1 associates with tumour progression, size and invasiveness and involves in multiple cellular processes of apoptosis, cell proliferation and migration." (PMID 37246623, 2023). "In contrast, the rather low frequencies of UCHL1 copy number alterations or somatic mutations across tumor entities formally exclude a strong impact of genetic alterations on UCHL1 expression or function." (PMID 36980544, 2023). "Consistent with previous bioinformatics analysis, silencing of UCHL1 is associated with tumor cell proliferation, migration, invasion, and poor prognosis of patients." (PMID 35546675, 2022). "A critical role of UCHL1 in neurogenesis in the embryonic brain has been reported, we then analyzed the association of UCHL1 with NB tumor differentiation in the TMA cohort." (PMID 30359286, 2018). "Ubiquitin carboxyl-terminal hydrolase 1 (UCHL1) belongs to the family of de-ubiquitinating enzymes (DUBs), deregulation of which causes tumor- inhibiting or -promoting functions in human cancer cells." (PMID 25971332, 2015). "In the present study, we provided a novel insight into the regulatory mechanism underlying tumour metastasis via activation of the Ubiquitin C-terminal hydrolase-L1 (UCHL1)-HIF-1 pathway." (PMID 25615526, 2015). "In the present study, we provided a novel insight into the regulatory mechanism underlying tumour metastasis via activation of the UCHL1-HIF-1 pathway." (PMID 25615526, 2015). "In primary tumors, UCHL1 methylation was associated with clinical stage and progesterone receptor status, indicating its potential as tumor marker for this cancer." (PMID 22279545, 2012). "In RCC, UCHL1 overexpression is associated with tumor progression and an altered von Hippel Lindau gene expression." (PMID 19857250, 2009). "In certain tumor types UCHL1 expression is even associated with tumor progression and decreased survival rates of patients." (PMID 19857250, 2009). "Previous studies linked UCHL1 to the regulation of the cell cycle in tumor growth and progression." (PMID 41155583, 2025). "In addition, UCHL1-related HNSC possessed an elevated tumor mutational burden (p < 0.001) with significant differences in the relative frequency of somatic mutations for selected MutSig genes (q-value < 0.05) of the TCGA-HNSC cohort." (PMID 36980544, 2023). "Growing evidence illustrated that the methylation status and deubiquitinating activity of UCHL1 were associated with patients’ prognosis, and its higher expression in tumor activated the Wnt-β-catenin/TCF pathway to promote cell proliferation, migration and invasion." (PMID 35655081, 2022). "Interestingly, a significantly positive correlation between the expression of UCHL1 and Ki-67-indicated UCHL1 was associated with tumor migration and invasion." (PMID 35546675, 2022). "However, the overexpressed c-myc in tumor cells was observed to have aggressive tumor growth due to UCHL1 that caused apoptotic resistance in hepatocarcinoma cells." (PMID 34769401, 2021). "UCHL1 exerts tumor suppressor function by inducing K48-linked ubiquitination of CTTN." (PMID 33585209, 2020). "However, UCHL1 expression in NB tumor cells and the association between UCHL1 expression with clinicopathologic features and survival of NB patients are not well understood." (PMID 30359286, 2018). "Furthermore, it has been reported that UCHL1 overexpression is associated with tumour progression, size and invasiveness." (PMID 21999842, 2011).
tumor (continued). "6RK73, with the molecular formula C13H17N5O2S, is a covalent, irreversible, and specific inhibitor of UCHL1, a deubiquitinase that plays a dual role in tumor progression." (PMID 41584043, 2026). "Despite this finding, it has been well documented that UCHL1 possesses dual functions as either an oncogene or tumor suppressor." (PMID 40078282, 2025). "Based on prior studies, UCHL1 is a bifunctional regulator, acting either as a tumor suppressor or promoter depending on the tumor type." (PMID 41155583, 2025). "In this current investigation, we observed a decrease in activated tumor growth pathways in chemoresistant PEA2 HGSOC cells following UCHL1 small-molecule inhibition." (PMID 40078282, 2025). "Some studies have identified UCHL1 as either an oncogene or a tumor suppressor, depending on the context." (PMID 40141757, 2025). "Next, we sought to assess tumor cell viability following UCHL1 small-molecule inhibition and carboplatin treatment in HGSOC cell lines." (PMID 40078282, 2025). "Collectively, our findings support a mechanism through which UCHL1 promotes tumor progression by modulating the CIP2A-c-Myc-cyclin signaling cascade." (PMID 41155583, 2025). "To follow up on our cell viability results, we performed Western blot analysis to observe how common tumor cell growth pathways are affected by UCHL1 small-molecule inhibition in both chemosensitive (PEA1) and chemoresistant (PEA2) cells." (PMID 40078282, 2025). "Taken together, this study demonstrates the anti-tumor efficacy of small molecule UCHL1 in HGSOC, specifically in the context of chemoresistance." (PMID 40078282, 2025). "Recently, scRNA-Seq analyses performed on nodular and diffuse pNFs revealed the presence of CAFs (Fb population transiently present in dyNFs) and of tumor SC expressing dyNF markers (Moxd1 and Uchl1) only in nodular NFs (unpublished results)." (PMID 41223283, 2025). "Compared with non-smokers, the content of this protein demonstrated almost a 20-fold increase, suggesting a special role of UCHL1 in the early stages of tumor transformation of the epithelium." (PMID 39940785, 2025). "Western blot analysis of neuronal marker UCHL1 in tumor lysates revealed lower levels in clone B3 and C4 tumors than in WT tumors, with clone B3 tumors showing the lowest UCHL1 levels, correlating with smaller tumor size." (PMID 39184078, 2024). "Several UCHL1 substrates have been described in tumour cells including Epidermal Growth Factor Receptor (EGFR), Transforming Growth Factor β (TGF-β), SMAD2, and importantly for our current study, Hypoxia Inducible Factor 1 α (HIF1α)." (PMID 38808772, 2024). "In summary, these findings provide a novel function of integrin α6β4 in promoting tumor invasive phenotypes through UCHL1-Hif-1α-mediated regulation of PTPRZ1." (PMID 39518121, 2024). "Current therapeutic approaches targeting UCHL1 in CCRCC include investigating its role in tumor growth and resistance to treatments like bevacizumab." (PMID 39199615, 2024). "In this study, we applied comprehensive in silico analysis to describe a new group of UCHL1-related cancers with shared molecular characteristics and vulnerabilities across tumor entities, establishing a foundation for treatment improvements." (PMID 36980544, 2023). "Consistently, UCHL1 shRNAs treatment significantly impaired tumor cell migration and invasion in Transwell/cellular invasion experiments." (PMID 37815895, 2023). "Then cellular proliferation CCK8 in combination of colony formation assays were conducted and results indicated that UBC cells treated with UCHL1-specific shRNAs significantly suppressed tumor cell proliferation and colony formation." (PMID 37815895, 2023).
tumor (continued). "Altered UCHL1 expression and function have been reported in several cancers, providing growing evidence for its contribution to tumor biology." (PMID 36980544, 2023). "In cancer, UCHL1 has been described to act as a tumour suppressor, as it was silenced in several cancer types, such as prostate cancer, ovarian cancer, and nasopharyngeal carcinoma." (PMID 38016026, 2023). "UCHL1-related primary tumors showed significantly fewer overall events (tumor recurrence) within 24 months." (PMID 36980544, 2023). "The upregulation of CHGA and UCHL1, which play a critical role in the oxidative stress response—an anti‐apoptotic function, is a unique feature of tumour cells." (PMID 37246623, 2023). "UBC tumor cells with UCHL1 shRNAs treatment exhibited significantly suppressed relative migration ratio, compared with control group." (PMID 37815895, 2023). "ELN, EFEMP1, and UCHL1 were expressed at low levels whereas TP63 was expressed at high levels in tumor tissues in contrast with ANT." (PMID 37441420, 2023). "The IHC scores indicated that UCHL1 was upregulated in the tumor tissue compared with the normal tissues." (PMID 35546675, 2022). "Immunohistochemical analysis showed that the expression of UCHL1 was positively correlated with Ki-67 and promoted tumor proliferation." (PMID 35546675, 2022). "Then, IHC staining of SENP1 and UCHL1 was performed to evaluate their physiological relevance to AR and tumour progression." (PMID 35452181, 2022). "There has been much debate over the role of UCHL1 in cancer, with reports proposing oncogenic or tumour suppressor roles, but a full discussion of these works is not within the scope of the review." (PMID 34497382, 2022). "Our findings initiated future research for the rediscovery of MSCs, cancers/tumours and the UCHL1-induced apoptosis." (PMID 35865633, 2022). "Multiplex fluorescent IHC staining of TTF1 and UCHL1 on tumor tissues from P11 also verified the coexpression of these two markers in a high proportion of tumor cells." (PMID 35962452, 2022). "Deubiquitinase enzyme “UCHL1” presented a contradicting action in tumor cells, having oncogenic and suppressor effects." (PMID 34769401, 2021). "We further explore the TCGA database and uncloaked that although UCHL1 statistically decreased in ccRCC compare to the normal, it was gradually increasing consistent with tumor grade." (PMID 34016791, 2021). "The deubiquitinating enzyme UCHL1 was recently found to play important roles in chemoresistance and tumor progression." (PMID 32483437, 2020). "H&E staining exhibited that the primary tumors in the UCHL1 knockdown group showed a more aggressive phenotype with invasion of the tumor cells towards the skin and muscle than the tumors in the shControl group." (PMID 32120844, 2020). "Later studies have reported UCHL1 expression in cells of the diffuse neuroendocrine system, testis and certain tumours." (PMID 31932518, 2020). "Treatment of USC-bearing mice with the UCHL1-specific inhibitor reduced tumor growth and improved overall survival." (PMID 31906456, 2020). "For example, UCHL1 strengthens tumor cells chemosensitivity in melanoma and colorectal cancer by stabilizing NOXA." (PMID 33585209, 2020). "For example, UCHL1 has been controversially considered as a tumor suppressor or tumor promoter in specific tumor types." (PMID 33585209, 2020). "Mice injected with SUNE1 stably overexpressing UCHL1 exhibited significantly reduced metastatic tumor colonies in the lung compared to those injected with control cells." (PMID 32120844, 2020). "Our findings revealed that UCHL1 acts as a tumor suppressor gene in NPC and thus provided a novel therapeutic target for NPC treatment." (PMID 32120844, 2020).
tumor (continued). "UCHL1 silencing led to a decrease in cell proliferation both in vitro and in vivo, while UCHL1 inhibition reduced tumor growth and improved survival in vivo." (PMID 31906456, 2020). "Our data show significant suppression of UCHL1 in tumor tissues, in agreement with a previous report, further consolidating its value in PCa biology." (PMID 31495056, 2019). "Methylation inactivation of tumor suppressors such as UCHL1 and TUSC3 were diagnosed with EOC.IFI27 was responsible for the proliferation of epithelial cancer cells.Li IFI27 was associated with invasion and drug resistance in EOC." (PMID 30970615, 2019). "Except for UCHL1 and HNRNPA2B1, we found that the high transcriptional levels of the rest of the selected genes are associated significantly with a decrease in tumor burden." (PMID 31551755, 2019). "The aberrant overexpression of UCHL1 facilitated distant tumor metastases in a HIF-1-dependent manner in breast and lung cancer." (PMID 30359286, 2018). "UCHL1 was differentially expressed in different samples of neuroblastic tumor patients, according to which patients were classified into UCHL1 high or UCHL1 low based on IHC score." (PMID 30359286, 2018). "The correlation between clinical characteristics, survival and the deubiquitinating enzyme ubiquitin C-terminal hydrolase 1 (UCHL1) expression were assessed using a neuroblastic tumor tissue microarray, and then validated in three independent patient datasets." (PMID 30359286, 2018). "UCHL1 was also recently studied in cancers, and was considered as either an oncogene or a tumor suppressor gene depending on the tumor types." (PMID 30359286, 2018). "Based on our neuroblastic tumor tissue microarrays and three independent validation datasets (Oberthuer, Versteeg and Seeger), we identified that UCHL1 served as a prognostic marker for better clinical outcome in NB." (PMID 30359286, 2018). "In this regard, UCHL1 is differentially expressed in various cancers, and has been proposed to have oncogenic or tumor suppressive properties depending on the cellular context." (PMID 28472177, 2017). "Taken together, these results indicated that UCHL1 is a good therapeutic target for the suppression of distant tumour metastases." (PMID 25615526, 2015). "This study explored the role of ubiquitin C-terminal hydrolase-L1 (UCH-L1) in the production of ROS and tumor invasion." (PMID 25915537, 2015). "Tumour samples were categorized into three groups (high, intermediate and low) according to the expression levels of UCHL1 and HIF-1α, respectively." (PMID 25615526, 2015). "The aberrant expression of UCHL1 was shown to promote distant tumour metastasis via the activation of HIF-1." (PMID 25615526, 2015). "The aberrant overexpression of UCHL1 facilitates distant tumour metastases in a HIF-1-dependent manner in murine models of pulmonary metastasis." (PMID 25615526, 2015). "We subsequently investigated the influence of the UCHL1-mediated activation of HIF-1 on tumour malignancy." (PMID 25615526, 2015). "Tumour samples were categorized into four groups (+++, ++, +, −) according to the expression levels of UCHL1 and HIF-1α, respectively." (PMID 25615526, 2015). "The high expression of UCHL1 in primary keratinocytes carrying infectious hrHPV is generally lost after transformation of these keratinocytes to tumor cells." (PMID 23717208, 2013). "Recent studies have shown that UCHL1 methylation is correlated with tumor cell differentiation, lymph node metastasis and poor prognosis, thus as a tumor marker." (PMID 22279545, 2012). "UCHL1 exerts its tumor suppressive functions by inducing G0/G1cell cycle arrest and apoptosis in breast tumorigenesis, requiring its deubiquitinase activity." (PMID 22279545, 2012).